TRPM7 (transient receptor potential cation channel subfamily M member 7)
Diseases named in the same sentence as TRPM7 in open-access papers (continued):
Sharing a sentence is not in itself a finding about the gene and the disease.
Stroke (17 papers, 2010 to 2025). Sudden impairment of blood flow to a part of the brain due to occlusion or rupture of an artery to the brain. "Dysregulation of neuronal TRPM7 activity has been associated with familial Alzheimer's disease, Parkinson's disease and stroke." (PMID 30453391, 2019). "Several TRPM channels, such as TRPM2, TRPM4, and TRPM7 have been implicated in stroke." (PMID 36527242, 2023). "Dysregulation of TRPM7 contributes to the pathophysiology of a large variety of disorders, especially cancer, cardiovascular defects, and neuronal injury caused by stroke and traumatic brain injury." (PMID 34928937, 2021). "Adipose-derived stem cell exosomes are rich in microRNA-181b-5p, which regulates angiogenesis after a stroke by inhibiting transient receptor potential melastatin 7 (TRPM7)." (PMID 40771978, 2025). "Though direct evidence in stroke models is limited, their ability to modulate TRPM7 suggests promising neuroprotective potential warranting further investigation." (PMID 41357867, 2025). "In the process of brain and myocardial injury, the increased expression of TRPM7 leads to the apoptosis of neurons and cardiomyocytes, while inhibition of TRPM7 can alleviate the stroke and myocardial injury." (PMID 36705408, 2023). "Previous studies have highlighted the importance of TRPM7 channels in brain diseases such as stroke and traumatic brain injury, yet evidence for a role in seizures and epilepsy is lacking." (PMID 37328275, 2023). "TRPM7 activity is greatly enhanced after ischemia/hypoxia, possibly due to both TRPM7 protein upregulation and channel potentiation owing to the stroke‐induced acidic environment." (PMID 36527242, 2023). "In the CNS, TRPM7 was first discovered in microglia, and more recently has been proposed as a therapeutic target to reduce neurodegeneration after stroke." (PMID 25148577, 2014). "By leveraging advanced drug delivery systems, developing selective inhibitors, improving preclinical study designs, and exploring biomarker-guided therapies, the therapeutic potential of carvacrol or TRPM7-targeted strategies can be fully realized, facilitating effective stroke treatments." (PMID 41357867, 2025). "Alternatively, it cannot be excluded that the neuroprotective effect in stroke of miR135a may be attributable also to other targets, different from TRPM7." (PMID 37718696, 2024). "Therefore, an alternative strategy to develop safe drugs against TRPM7 function in stroke would be a selective targeting of the kinase activity of TRPM7, thereby inhibiting thrombo-inflammation and protecting BBB and neurons from ischemic insults." (PMID 31652790, 2019). "Indeed, blocking TRPM7 channels or suppressing its expression by RNA interference was effective in preventing the death of neurons in stroke." (PMID 30459705, 2018). "Collectively, these studies strongly suggest that TRPM7 may be an effective pharmacological target for stroke treatment; however, compounds that could potentially be used clinically against the channel have not been identified." (PMID 20567598, 2010). "Therefore, carvacrol may be a useful therapeutic agent for preventing stroke-induced neuronal death, and the TRPM7 channel is a novel target for treating neurological disorders." (PMID 30486272, 2018). "However, since previous studies have also implicated TRPM7 in the Ca2+-mediated neuronal injury after ischemic stroke, further work will be needed to clarify which of the two proposed cations flowing through TRPM7 is (more) responsible for the pathological consequences of stroke." (PMID 25106481, 2015).
Hypomagnesemia (16 papers, 2017 to 2025). An abnormally decreased magnesium concentration in the blood. "We report three new heterozygous missense variants in TRPM7 (p.Met1000Thr, p.Gly1046Arg, p.Leu1081Arg) in individuals with hypomagnesemia." (PMID 39099563, 2024). "This study provides additional evidence for the association between heterozygous TRPM7 variants and hypomagnesemia and adds developmental delay to the phenotypic spectrum of TRPM7-related disorders." (PMID 39099563, 2024). "In this study, we provide evidence that heterozygous pathogenic TRPM7 variants are causative for hypomagnesemia and can also be associated with developmental delay and ASD." (PMID 39099563, 2024). "Recently, two independent groups identified heterozygous variants in the TRPM7 gene in three families with hypomagnesemia (serum Mg2+ <0.7 mmol/L)." (PMID 39099563, 2024). "TRPM6 is very important for Mg2+ uptake; TRPM6P1017R mutation impairs channel activity of TRPM6/TRPM7 heteromers, which leads to hypomagnesemia." (PMID 35813831, 2022). "Heterozygous variants in Transient receptor potential melastatin type 7 (TRPM7), encoding an essential and ubiquitously expressed cation channel, may cause hypomagnesemia, but current evidence is insufficient to draw definite conclusions and it is unclear whether any other phenotypes can occur." (PMID 39099563, 2024). "Diminished active Magnesium transport in the colon, primarily mediated by the ion channels TRPM6 and TRPM7, serves as the principal explanation for proton pump inhibitor-related hypomagnesemia." (PMID 40291321, 2025). "We found hypomagnesemia and reduced phosphorylation of TRPM7-kinase in WT mice treated with aldosterone and salt, phenomena observed in TRPM7+/Δkinase animals in basal unstimulated conditions." (PMID 35882956, 2022). "Under hypomagnesemia, low serum (i.e., extracellular) Mg levels can activate Mg transporters such as TRPM7 and SLC41A1 to induce Mg efflux from cells to increase serum Mg levels." (PMID 32977544, 2020). "In vivo experiments in mice provide evidence that the specific TRPM7 inhibitor waixenicin A, given as a single bolus injection, induces transient hypomagnesemia and increases intestinal absorption of calcium." (PMID 28810912, 2017). "Thus, the activity of TRPM6 has been indicated to be dependent on the expression of TRPM7, while mutations in TRPM6 appear to induce hypomagnesemia with secondary hypocalcemia." (PMID 39614204, 2024). "Considering both TRPM proteins are co-expressed highly in the colon and DCT, it is likely that in both cases the underlying mechanism of the hypomagnesemia is intestinal malabsorption and renal wasting caused by decreased functioning of TRPM6/TRPM7 heterotetramers." (PMID 39099563, 2024). "TRPM7 is implicated in ischemic stroke and hypomagnesemia in many studies, but it has not been associated with disease in the OMIM database." (PMID 35712613, 2022). "Although rare, chronic use of proton pump inhibitors (PPIs) can cause hypomagnesemia due to impaired intestinal absorption, mainly attributed to reduced transcellular transport of magnesium via transient receptor potential melastatin 6 (TRPM6) and 7 (TRPM7) channels." (PMID 38222324, 2024). "No clinical cases between TRPM7 gene variants and hypomagnesemia have been reported, so far." (PMID 35712613, 2022). "Thus, waixA successfully induces hypomagnesemia, thereby implicating TRPM7 in the process." (PMID 28810912, 2017). "Therefore, we considered that CBGA might induce hypomagnesemia in vivo through TRPM7 blockage." (PMID 37072467, 2023). "In addition, it is possible that the CBGA concentrations reached in vivo may not have sufficed to reduce TRPM7 magnesium transport to cause hypomagnesemia either through channel block or protein downregulation or both." (PMID 37072467, 2023). "Mechanisms for hypomagnesemia include increased intestinal mRNA expression of TRPM6, TRPM7, and SLC41A1 and therefore increased Mg extrusion." (PMID 32977544, 2020).
Hypomagnesemia (continued). "In mice, maternal hypomagnesemia did not change the activity of TRPM7 and TRPM6 ion channels but increased the expression of placental MagT1 transporter and Ca-selective channels (TRPV6), which probably increases the levels of Mg in the placenta and maintains its function in Mg deficiency." (PMID 30717440, 2019). "However, mice did not have exhibit hypomagnesemia at day 3 after we injected CBGA 3 times, even though CBGA suppressed TRPM7 expression in nephropathic kidneys in this study." (PMID 37072467, 2023).
ischemia (15 papers, 2010 to 2025). A hypoperfusion of the BLOOD through an organ or tissue caused by a PATHOLOGIC CONSTRICTION or obstruction of its BLOOD VESSELS, or an absence of BLOOD CIRCULATION. "Two studies explored the role of carvacrol in modulating TRPM7 channels, which are implicated in neuronal death during ischemia." (PMID 41357867, 2025). "TRPM7 could emerge as a new drug target to be explored in retinal pathologies associated with ischemia." (PMID 38003256, 2023). "Our main purpose was to analyze if the transient receptor potential channel 7 (TRPM7) could contribute to retinal dysfunction in retinal pathologies associated with ischemia." (PMID 38003256, 2023). "Carvacrol demonstrates promising neuroprotective signals in both focal and global ischemia models, with convergent antioxidant and anti-apoptotic effects and suggestive TRPM7 involvement." (PMID 41357867, 2025). "Carvacrol shows neuroprotective signals across focal and global ischemia models, with consistent antioxidant and anti-apoptotic effects and suggestive TRPM7 involvement." (PMID 41357867, 2025). "The brain constitutively active isoform of transient receptor potential melastatin 7 (TRPM7) represents a glutamate excitotoxicity‐independent pathway that significantly contributes to the pathological Ca2+ overload during ischemia." (PMID 37718696, 2024). "Our results show that ischemia elicited a decrease in retinal responsiveness to light stimuli along with reactive gliosis and a significant increase in the expression of TRPM7 in Müller cells." (PMID 38003256, 2023). "Suppression of TRPM7 expression reduces the cleaved caspase-3 in the brain following ischemia in mice." (PMID 35406741, 2022). "TRPM7 plays a key role in a variety of diseases, including neuronal death in ischemia, cancer, cardiac atrial fibrillation, malaria invasion." (PMID 32047249, 2020). "This work was subsequently followed by experiments to demonstrate the protective effect of knockdown of TRPM7 by RNA interference following ischemia using an in vivo model." (PMID 20567598, 2010). "The earlier study demonstrated that knockdown of TRPM7 dramatically reduced neuronal cell death induced by oxygen glucose deprivation (OGD) using an in vitro model of ischemia." (PMID 20567598, 2010). "In ischemia, TRPM7 acts as a master amplifier of neuronal injury." (PMID 41357867, 2025). "In the light of these premises, finding a way to reduce TRPM7 activation during ischemia may be a reasonable strategy to reduce ischemic injury." (PMID 37718696, 2024). "This hypothesis may support the idea that reducing TRPM7 levels in an early phase after ischemia onset, before the damage has been established, may confer neuroprotection." (PMID 37718696, 2024). "Furthermore, the post-ischemia increase in TRPM7 expression was higher in PV neurons than that in glutamatergic neurons." (PMID 35406741, 2022). "Therefore, global inhibition or suppression of TRPM7 in neural systems exerts neuroprotective effects against ischemia." (PMID 35406741, 2022). "In conclusion, we found that, in comparison with glutamatergic neurons, knockout of TRPM7 in GABAergic PV neurons has better neuroprotective and/or recovery effects following ischemia as well as stronger activation of anti-oxidative stress signaling within the post-ischemic brain." (PMID 35406741, 2022). "This suggests that one of the mechanisms by which TRPM7 might be producing its pathological effect after ischemia/reperfusion is through the activation of RhoA." (PMID 33240883, 2020). "Moreover, TRPM7 blockage by carvacrol prevented brain damage in a mouse hypoxia-ischemia brain injury model." (PMID 33240883, 2020). "Downregulation of TRPM7 is neuroprotective following global ischemia." (PMID 21052549, 2010). "The function of TRPM7 channels is usually attributed to one of Mg2+ homeostasis but they are also a source of entry of Ca2+ and contribute to the death of hippocampal neurons following ischemia." (PMID 21122141, 2010).
ischemia (continued). "However, increased zinc influx through TRPM7 may lead to neuronal cell death in conditions like ischemia, creating a debate about the protective versus harmful effects of TRPM7-mediated zinc influx." (PMID 39301907, 2025). "Indeed, TRPM7 is able to sense the extracellular concentration of divalent ions and to maintain intracellular Mg2+ homeostasis during episodes that lead to intense neuronal activity, such as ischemia." (PMID 37718696, 2024). "Therefore, deleting TRPM7 in GABAergic PV neurons might have stronger neuroprotective effects against ischemia pathologies than doing so in glutamatergic neurons." (PMID 35406741, 2022). "The ischemia-induced upregulation of TRPM7 expression was found to be higher in GABAergic PV neurons than in glutamatergic neurons, which might explain the sensitivity of GABAergic PV neurons to ischemia-induced neuronal death." (PMID 35406741, 2022). "However, a change in TRPM7 protein expression and/or in channel modulation due to modified cellular signalling during acute ischemia may also affect the contribution the channels." (PMID 28129376, 2017). "Carvacrol, a pungent natural compound often used as a food additive, has been reported to block TRPM7 current in HEK cells over-expressing TRPM7 and in hippocampal neurons, as well as provide neuroprotection in adult mice subjected to focal ischemia." (PMID 25761704, 2015). "The capacity of NM, HSB and DAPI to block TRPM7 current suggests a molecular structure which might be explored for the development of agents that block the contributions of these currents to the pathophysiological over activation of central neurons in epilepsy and/or ischemia." (PMID 21122141, 2010). "During the 7 days post-ischemia period, we found that TRPM7 knockout in PV (PV-TRPM7−/−: 93.8%) and CaMKII (CaMKII-TRPM7−/−: 92.3%) neurons resulted in clear enhancement of animals’ survival rate in comparison with that of TRPM7flox/flox MCAO (control group: 63.6%)." (PMID 35406741, 2022). "Additional research has demonstrated that TRPM2, TRPM6, TRPM7, and TRPM8 may impact hepatic ischemia-reperfusion injury, with TRPM2 knockout exhibiting a reduction in such injury through the activation of autophagy and inhibition of autophagy-negative regulation of the NLRP3 inflammasome pathway." (PMID 38255767, 2024). "Therefore, we concluded that ischemia-induced neurological and motor deficits are reduced by the deletion of TRPM7 in GABAergic PV neurons, but not in glutamatergic neurons." (PMID 35406741, 2022). "Finally, we measured TRPM7 channel expression after GCI, and whether carvacrol could inhibit TRPM7 channel expression after ischemia." (PMID 30486272, 2018). "TRPM7’s role in differentiated, non-proliferating tissue seems to be at variance from that seen in proliferative cell types; For example, suppression of TRPM7 protects hippocampal neurons from death in ischemia." (PMID 28810912, 2017). "Of these subtypes the TRPM7 and to a lesser extent TRPM2 members are the most important with respect to ischemia-induced neuronal calcium influx, as these receptors are activated by oxidative mechanisms which are increased during ischemia and result in large intracellular calcium influxes." (PMID 21052549, 2010).
lung carcinoma (15 papers, 2013 to 2025). "More recently, the TRPM7/O-linked-β-N-acetyl glucosaminylation (O-GlcNAcylation) axis was suggested to represent a novel target for lung cancer therapy." (PMID 38255793, 2024). "In this study, we found that the Ca2+-permeable cation channel TRPM7, which is associated with progression and poor prognosis in lung cancer patients, is a key regulator of NSCLC cell migration and invasion and overall metastatic activity." (PMID 32684624, 2020). "In lung cancer cells, TRPM7 expression was increased and associated with enhanced SOX2, KLF4, and CD133, Hsp90α, uPA, and MMP2." (PMID 30995736, 2019). "Our results showed that downregulation of TRPM7 protein expression in the lung cancer cells, was associated with concomitant downregulation of vimentin mRNA expression, while the mRNA expression of E-cadherin, p21 and BAK was upregulated." (PMID 30477473, 2018). "Furthermore, aberrant TRPM7 expression is associated with poor lung cancer prognosis, with its overexpression playing a critical role in tumor cell migration and invasion." (PMID 40002176, 2025). "Bioinformatics analysis of an association between TRPM7 expression and staging of human lung carcinoma revealed that high TRPM7 correlates well with lymph node metastasis (stage N0 versus N2) and thus further support the role of TRPM7 in the progression of lung cancer." (PMID 32684624, 2020). "It is also possible that the surface Hsp90 interacts with the extracellular domain of TRPM7; thus, the disruption of this Hsp90/TRPM7 interaction results in the inhibition of cell invasion and associated with altered actin dynamics in the human lung cancer cells." (PMID 30477473, 2018). "Subsequent studies have shown that TRPM7 operates through a similar regulatory mechanism in lung cancer." (PMID 39633507, 2024). "Role of the TRPM7 chanzyme in the pathophysiology of lung cancer and of the neoplasms of the urinary tract." (PMID 38255793, 2024). "Waixenicin A, a TRPM7 inhibitor, also suppressed the cancer stem cell phenotype of lung cancer cells." (PMID 38255793, 2024). "Analogously, in cancer stem (CSCs)-like and metastatic lung cancer cells, TRPM7 silencing induced EMT inhibition, stemness markers, phenotypes suppression, and concomitantly Hsp90α/uPA/MMP2 deregulation." (PMID 36844925, 2022). "Another supporting study showed that TRPM7 overexpression resulted in the increased expression of cancer stemness markers such as SOX2, KLF4, and CD133 in lung cancer, while TRPM7-silencing led to the reduction of stemness and EMT traits." (PMID 35771152, 2022). "Increased TRPM7 expression was associated with enhanced SOX2, KLF4, CD133, Hsp90α, uPA, and MMP2 expression in lung cancer stem cells." (PMID 36142596, 2022). "TRPM7 inhibition also decreases Cav-1 expression, a component of the plasma membrane micro-domains, overexpressed in lung carcinoma, and connected with tumor invasiveness and patients’ poor survival." (PMID 36844925, 2022). "Consistent with the findings obtained from NSCLC cell lines, we observed a dose-dependent decrease in cell migration upon TRPM7 inhibition in multiple primary lung cancer cells." (PMID 32684624, 2020). "Having shown that TRPM7 expression is relevant in the pathogenesis and prognosis of lung cancer, as well as inhibitory effects of TRPM7 knockdown in lung cancer cells, we then investigate the effect of TRPM7 inhibitor, Waixenicin A on the TRPM7-rich 95D cells." (PMID 30477473, 2018). "In furtherance of our functional characterization of TRPM7 in lung cancer, we knocked down TRPM7 in A549 or 95D cells using the short hairpin RNA." (PMID 30477473, 2018). "Increased TRPM7 expression was associated with enhanced SOX2, KLF4, and CD133, Hsp90α, uPA, and MMP2 expression in lung cancer cells." (PMID 30477473, 2018). "Our data confirm that Waixenicin A inhibits native TRPM7 currents in both lung cancer cells and its counterpart lung cancer spheres." (PMID 30477473, 2018).